IGFBP2 (insulin like growth factor binding protein 2)
Diseases named in the same sentence as IGFBP2 in open-access papers (continued):
Sharing a sentence is not in itself a finding about the gene and the disease.
glioma (continued). "In glioma, IGFBP2 is often involved in the activation of PTEN, AKT and other related pathways, leading to enhanced invasiveness and malignancy." (PMID 36110851, 2022). "The IGFBP2-positive macrophages/microglia frequently accumulate near the focal necrosis areas of glioma, suggesting an important immune action for IGFBP2 in glioma." (PMID 36556226, 2022). "IGFBP2 is considered as one of the three most promising blood markers for glioma, and future studies will focus more on the mechanisms of IGFBP in glioma." (PMID 35992105, 2022). "Our previous research established that IGFBP2 potentiates STAT3 transactivation activities by increasing nuclear EGFR amounts in glioma." (PMID 36556226, 2022). "IGFBP2 also acts as a tumor promoter in glioma and pancreatic cancer by activating nuclear EGFR-STAT3 signaling." (PMID 34572779, 2021). "In malignant tumors such as prostate cancer, high-grade glioma, and hepatocellular carcinoma, high expression of IGFBP2 was correlated to poor prognosis." (PMID 34572779, 2021). "A neutralizing antibody against IGFBP2 was reported to inhibit the malignant phenotype of glioma in vitro and in vivo." (PMID 34572779, 2021). "The IGFBP2 is said to be one of most potential glioma oncogenes and functions as a hub of oncogenic signaling pathways by regulating pro-tumorigenic signals of tumor initiation and progression." (PMID 34211498, 2021). "Different studies demonstrate that IGFBP-2 is overexpressed in glioma cells showing a distinct progression-related expression change from low- to high-grade gliomas." (PMID 33604294, 2020). "Previous results suggested that EMP3 28-32 and IGFBP2 33-35 were critical biomarkers in glioma prognosis." (PMID 32328202, 2020). "FcγRIIB expression was significantly correlated with the enrichment score of the mesenchymal signature (R = 0.7919, p < 2.2e-16) and moderately with IGFBP2 expression (R = 0.22, p < 0.012) in gliomas." (PMID 31560714, 2019). "IGFBP2 therefore remains as a candidate biomarker and potential therapeutic target in glioma therapy, perhaps immunotherapy in particular." (PMID 31296788, 2019). "In this study, we investigated the significance of IGFBP2-induced EMT in antitumor immune responses in a GL261 model of glioma." (PMID 31560714, 2019). "As mentioned, IGFBP2 overexpression is common in high-grade glioma and IGFBP2 is a prognostic factor for poor survival." (PMID 31296788, 2019). "In human glioma, the insulin-like growth factor binding protein-2 (IGFBP2), circulating in the serum of patients or endogenously produced by the tumor, activates ERK1/2 and determines resistance to temozolomide by favoring the entrance into S- and G2/M-phases." (PMID 31117237, 2019). "Exogenous IGFBP2 increases the proliferation and invasive capacity of the glioma cells, and induces chemoresistance, while knockdown of IGFBP2 resulted in both decreased invasiveness and tumorigenicity in nude mice." (PMID 31296788, 2019). "Recently, IGFBP2 has been put forward as a specific prognostic marker in IDH-mutant low-grade glioma patients." (PMID 31296788, 2019). "Whereas opposite results have been reported in MCF7 and T47D breast cancer cells, hepatocellular carcinoma and glioma cells where IGFBP-2 acted to promote cell growth." (PMID 31903164, 2019). "The enrichment score of the mesenchymal signature of gliomas was significantly positively correlated with IGFBP2 expression in human gliomas (R = 0.6812, p < 2.2e-16)." (PMID 31560714, 2019). "In the PDGF-driven TV-A rat tumors, the glioma-related genes IGFBP2 and BMP7 were uniquely under-expressed compared to the other three species." (PMID 29352201, 2018). "For low-grade glioma cases with an actionable mutation, protein profiles of EGFR_pY1068, HER2_pY1248, HER2, IGFBP2, EGFR_pY1173, and STAT5-alpha are decreased." (PMID 30442178, 2018). "Glioma-associated DEGs CD244, IL21, RET, TGFA were up-regulated and AQP9, IGFBP2, EGFR, SOX9 were down-regulated specifically in the rat." (PMID 29352201, 2018).
glioma (continued). "To test further the specificity of IGFBP2, we also analyzed MYC, FOXM1, and E2F2, which have been associated with malignant progression of IDH-mutant glioma." (PMID 27852048, 2017). "Further studies demonstrated the important role of IGFBP2 in glioma progression and indicated that IGFBP2 expression was a poor prognostic marker in a mixed cohort ranging from grade II glioma to glioblastoma as well as in glioblastoma alone." (PMID 27852048, 2017). "We identified that NFIA-mediated IGFBP2 signaling pathways are involved in miR-302b-induced glioma cell death." (PMID 28323865, 2017). "Exogenous IGFBP2 promotes glioma-cell proliferation and invasion capability via the ERK pathway, which is activated by integrin β1 signaling." (PMID 28931862, 2017). "Elevated blood IGFBP2 level has been identified in various human malignancies such as ovarian cancer, prostate cancer, lung cancer, pancreatic cancer, glioma and colon cancer." (PMID 28036255, 2017). "Previous reports demonstrated increased expression of IGFBP2 in various types of cancer tissue, including glioma, colorectal cancer, lung cancer, and gastric cancer, and high expression of IGFBP2 was associated with worse survival." (PMID 28036255, 2017). "The suggestion that IGFBP2 is involved in glioma progression dates back to 1999 when IGFBP2 overexpression was discovered in glioblastoma." (PMID 27852048, 2017). "For example, Insulin-like growth factor-binding protein 2 (IGFBP2) has been considered as a glioma oncogene." (PMID 29050331, 2017). "According to our results, we conclude that inhibition of NFIA-mediated IGFBP2 signaling plays a crucial role in miR-302b-induced glioma U87-MG cell death." (PMID 28323865, 2017). "We compared the endogenous protein levels of IGFBP2 in normal astrocytes and three glioma cell lines." (PMID 28323865, 2017). "Both NFIA and IGFBP2 levels were higher in glioma cell lines and tumor tissues and were significantly associated with a poor survival rate." (PMID 28323865, 2017). "Higher protein levels of IGFBP2 from intracellular components and conditioned media were found in glioma cells than in normal astrocytes." (PMID 28323865, 2017). "ZEB1 is associated with malignancy in glioma and analysis of GBM patient specimens demonstrated that proinflammatory cytokines, such as CXCL12, IGFBP2, IL-1ß, TNF-a and MIF, correlate significantly with ZEB1 expression in tumor specimens." (PMID 28445977, 2017). "As expected, IDH-mutant gliomas manifested increased methylation concomitant with decreased expression of IGFBP2, YAP1, and WWTR1 in comparison with IDH-wildtype." (PMID 27852048, 2017). "In a continued effort to identify genes that are specifically associated with the survival of IDH-mutant gliomas, we examined IGFBP2, WWTR1, and YAP1, which are associated with glioma progression." (PMID 27852048, 2017). "Exogenous IGFBP2 promotes proliferation, invasion, and chemoresistance to temozolomide in glioma cells through the integrin β1-extracellular signal-regulated kinase pathway." (PMID 28323865, 2017). "NFIA-activated IGFBP2 expression also exhibited antagonistic effects on miR-302b-induced glioma cell apoptosis." (PMID 28323865, 2017). "The 89-gene signature consists of a number of hypoxia and inflammation-related genes such as AKR1C3, PTX3, PLAT and IGFBP2, showing that these two inseparable hallmarks are involved in tumor progression and play significant roles in glioma pathogenesis." (PMID 27323413, 2016). "Several serum biomarkers-YKL40, MMP9, B-chain of α2-Heremans-Schmid glycoprotein (AHSG), Haptaglobin α2, Osteopontin and IGFBP2 have been reported to identify glioma." (PMID 26390214, 2015). "Of the two Type 1 hits, MIIP (migration and invasion inhibitory protein) was initially identified in a yeast-two-hybrid screen as a binding partner for the insulin-like growth factor binding protein 2 (IGFBP2) and shown to inhibit glioma cell invasion." (PMID 26466362, 2015).
glioma (continued). "On the other hand, IGFBP2 overexpression is specific to glioblastoma multiforme compared to gliomas." (PMID 25884993, 2015). "IGFBP2 was reported to be overexpressed in glioblastoma and promote glioma tumor stem cell expansion and survival." (PMID 25845910, 2015). "These predictions strongly suggest redirecting the focus of glioma drug candidates on controlling the feedback between IGFBP2 and HIF1α." (PMID 25884993, 2015). "Our study showed endogenous cleavage of IGFBP2 in different tumor cell lines and, more importantly, in glioma samples by Western-blot and immunohistochemistry." (PMID 24962328, 2014). "Second, and more remarkable, all tested gliomas showed the cleaved form of IGFBP2 detected with the N-terminal antibody." (PMID 24962328, 2014). "Expression of IGFBP2 (Insulin-like Growth Factor Binding Protein 2) has been positively correlated with glioma progression." (PMID 24962328, 2014). "In fact, the extrapolation of our phosphorylation and migration assays supports that the proteolysis of IGFBP2 will be accompanied by increased bioavailability of IGFs in gliomas." (PMID 24962328, 2014). "On the other hand, it has been reported that IGFBP2 promotes the survival of glioma tumor stem cells, a hypothetical origin of trans-differentiation phenomenon." (PMID 24962328, 2014). "The results reported in this study provide a new area to be explored, proteolysis of IGFBP2 in gliomas." (PMID 24962328, 2014). "It has been found that preoperative plasma IGFBP-2 levels correlate with prognosis in glioma patients." (PMID 24690948, 2014). "Our results support a functional interaction between IGFBP2 and ADAMTS1 and suggest the need to evaluate post-translational modifications of IGFBP2 in glioma, in order to approach new therapies." (PMID 24962328, 2014). "The fact that all human glioma samples displayed proteolysis, some of them at very high rates, suggests the need to re-evaluate the claims of oncogenic attributes of IGFBP2." (PMID 24962328, 2014). "Here, a survival curve of glioma patients in relationship to their IGFBP2 gene expression data is shown; there are significant differences among high-, low- and intermediate-expressors (Log-rank p-value=6.564E-7, Up-regul." (PMID 24962328, 2014). "Nevertheless, it has been shown that intrinsic IGFBP2 interacts with integrin α5β1 and promotes migration of glioma cells and glioma progression through activation of AKT, ILK, and NF-κB pathways." (PMID 24191913, 2013). "Comparison of our data with a previous microarray study of IGFBP2 regulated genes in glioma cells revealed an overlap of about 22% genes with wild type IGFBP2 over expressing cells and 23% genes with RGE mutant IGFBP2 over expressing cells." (PMID 23767917, 2013). "IGFBP-2 is overexpressed in a majority of malignant tumors, including glioma and colorectal, prostate, ovarian and breast cancers." (PMID 23165420, 2013). "Primarily known for its growth inhibitory actions in physiological context, IGFBP2 has now been shown to promote growth and tumorigenesis in numerous cancer cells such as glioma, prostate and colon cancers." (PMID 23767917, 2013). "A recently published paper demonstrated that serum anti-IGFBP-2 antibody levels were significantly elevated in early cancer compared to advanced cancers in gliomas and colorectal carcinoma." (PMID 23165420, 2013). "IGFBP2 expression has also been shown to enhance migration and invasion in glioma, ovarian and bladder cancer cells." (PMID 23767917, 2013). "IGFBP2 over expression has been demonstrated to promote glioma growth as well as progression from low to high grade in mouse models." (PMID 20423517, 2010). "IGFBP2 was reported to play a key role in driving glioma cell growth via activation of the Akt pathway and to collaborate with K-Ras or platelet-derived growth factor β in the development and progression of glioma." (PMID 19087328, 2008).
glioma (continued). "The RGD motif in human IGFBP-2 has been reported to be involved in binding to integrin and this interaction is important for IGFBP-2-induced SNB19 glioma cell migration." (PMID 19081843, 2008). "IGFBP2 is also overexpressed in a wide spectrum of other cancers, including glioma, prostate cancer, synovial sarcoma, neuroblastoma, colon cancer, adrenocortical cancer, lung cancer, Wilms' tumor, and hepatoblastoma." (PMID 15686601, 2005). "The overexpression of IGFBP2 also correlates with the aggressiveness of some tumors, including prostate cancer, hepatoblastoma and glioma, suggesting that IGFBP2 possesses a carcinogenic property." (PMID 15686601, 2005). "IGFBP2 was also found to be co-expressed with the vascular endothelial growth factor in pseudopalisading glioma cells surrounding tumor necrosis." (PMID 15686601, 2005). "Similarly, the cancer-associated fibroblast (CAF)-related gene insulin-like growth factor-binding protein 2 (IGFBP2) plays a role in this process, as mentioned in gliomas." (PMID 40034694, 2025). "Notably, IGFBP2 is an established oncogene in various tumors including myeloid leukemia, gliomas, breast, and prostate cancer, and orchestrates multiple cancer signaling pathways such as PI3K-AKT, NF-κB, and EGFR/STAT3." (PMID 40193528, 2025). "IGFBP2 (Insulin-like growth factor 2 mRNA-binding protein 2), also known as IMP2, is an mRNA-binding protein that regulates a large number of cellular processes, and it is implicated in glioma progression by maintaining GSCs." (PMID 40507925, 2025). "IGFBP2 has been shown to increase glioma angiogenesis by upregulating MMP2 expression." (PMID 39903772, 2025). "Several studies have reported IGFBP-2 overexpression in glioma of increasing grade and aggression." (PMID 40429889, 2025). "IGFBP-2 is highly expressed in many cancers, including glioma." (PMID 39138166, 2024). "IGFBP2, which promotes vasculogenic mimicry formation in glioma, could be considered a key player in tumorigenesis." (PMID 37928523, 2023). "Early reports demonstrated that IGFBP2 is overexpressed in high grade gliomas." (PMID 37737709, 2023). "Targeting IGFBP2 could be a potential therapeutic strategy for treating gliomas by inhibiting its activity and slowing down tumor growth." (PMID 37928523, 2023). "Furthermore, rescue assays were conducted to explore the regulatory function of HOTAIRM1/METTL3/IGFBP2 in glioma cell cellular processes and VM formation." (PMID 38012763, 2023). "Notably, IGFBP2 was identified as a tumor promoter in gliomas, influencing tumor cell proliferation and migration, and also contributing to microglia migration." (PMID 37928523, 2023). "Recently, it was demonstrated that inhibition of IGFBP2 in U251 cells in an orthotopic mouse model significantly reduces angiogenesis mimic formation and inhibition of tumor progression, and IGFBP2 stimulates glioma cell angiogenic mimicry formation via CD144 and MMP2 up-regulation." (PMID 38012763, 2023). "Our findings suggest that in SHH medulloblastoma, as in glioma, IGFBP2 may regulate a STAT3-mediated EMT program in order to drive metastasis." (PMID 37029430, 2023). "IGFBP2 was successfully elevated or repressed in glioma cells." (PMID 38012763, 2023). "We then analyzed the expression of IGFBP2 in glioma tissues." (PMID 38012763, 2023). "IGFBP2 was found to promote glioma cell malignancy and VM formation." (PMID 38012763, 2023). "Correspondingly, our study revealed that IGFBP2 could promote the proliferation and migration of gliomas." (PMID 37928523, 2023). "Interestingly, highly expressing IGFBP2 samples showed enrichment in immune response-related pathways, indicating a potential immunogenic role for IGFBP2 in glioma." (PMID 37928523, 2023). "IGFBP2 interactions with integrin- α5 promote migration in glioma and Ewing’s sarcoma." (PMID 37029430, 2023). "Moreover, we also found that HOTAIRM1 silencing induced significant reduction in IGFBP2 expression in glioma cells." (PMID 38012763, 2023).
glioma (continued). "Notably, IGFBP2, identified as a glioma tumor promoter, was found to promote disease progression and influence immunotherapy response." (PMID 37928523, 2023). "IGFBP2 and IGFBP2-induced TRIM33 were associated with stemness induction of glioma cells." (PMID 36139694, 2022). "Accumulation of IGFBP2 can be found in activated microglia/macrophages, which are important glioma-infiltrating immune cells, and this may contribute to glioma development." (PMID 36556226, 2022). "Additionally, high IGFBP2 can act as a regulator of PD-L1 via the EGFR–STAT3 pathway and is associated with shorter overall survival in melanomas, while it has also been shown that IGFBP2 can activate the EGFR-STAT3 pathway in glioma." (PMID 35992105, 2022). "In our study, we also found that IGFBP2 is highly likely to be the oncogenic gene of glioma." (PMID 36110851, 2022). "SVOP and IGFBP2 may play different functions in different grades of gliomas and follow-up studies in these contexts are in progress." (PMID 35493457, 2022). "This may suggest that IGFBP2 is involved in processes related mainly to the migration and metastasis of tumor cells in the most advanced stage of gliomas." (PMID 35454784, 2022). "In terms of the survival curve, glioma patients with low expression of IGFBP2 had better survival, indicating that IGFBP2 may be a promoter of the malignant progression of glioma." (PMID 36110851, 2022). "Except for PD-1, CTLA4, and LAG3, the expression of other immunosuppression-related genes, such as LGALS1 and IGFBP2, is higher in glioma patients, and blocking the expression of immunosuppression-related genes can reshape the immunosuppressive microenvironment." (PMID 35928818, 2022). "Previous studies have confirmed that the expression levels of IGFBP2 transcripts and proteins are positively correlated with the malignant degree of glioma, suggesting that IGFBP2 plays an important role in malignant transformation, tumor necrosis and metastasis of glioma." (PMID 36110851, 2022). "IGFBP2 overexpression is common in high-grade glioma and is related to glioma progression." (PMID 36046036, 2022). "The 1-year (AUC=0.877), 2-year (AUC=0.92), 3-year (AUC=0.91), 4-year (AUC=0.858), and 5-year (AUC=0.822) survival ROC curves predicted by IGFBP2 revealed that the AUCs were all higher than 0.8, indicating the efficiency of IGFBP2 in predicting prognosis for glioma." (PMID 36110851, 2022). "Furthermore, in a study including 2447 glioma samples with gene expression profiles, IGFBP2 was found to be involved in immunosuppressive activities and was an independent unfavorable prognostic biomarker." (PMID 34805164, 2021). "However, the inner mechanisms of how EMP3 and IGFBP2 involving the glioma overall survival are unclear." (PMID 32328202, 2020). "Because of its overexpression, soluble IGFBP2 represents a good diagnostic and prognostic biomarker in several advanced cancers such as breast, glioma, ovarian, and lung cancer, eliciting a B cell-mediated immune response with the production of anti-IGFBP2 antibodies." (PMID 32093404, 2020). "Furthermore, we already suggested ADAMTS1 plays a role in glioma through its action on IGFBP2 (insulin-like growth factor-binding protein 2) but without any functional outcomes involving the plasticity of GBM cells." (PMID 33396280, 2020). "Interestingly, IGFBP2 is often upregulated in various cancer types, such as gliomas, prostate, ovarian, and breast cancer." (PMID 32133294, 2020). "The prognostic effects of EMP3 28-32 and IGFBP2 33-35 in glioma patients are extensively studied." (PMID 32328202, 2020). "It had been reported that IGFBP2 could promote glioma development and was also a critical biomarker in glioma prognosis 33-35." (PMID 32328202, 2020). "IGFBP2 re-emerges as a candidate biomarker and potential therapeutic target in glioma." (PMID 31296788, 2019).